CTNNB1 (catenin beta 1)
Diseases named in the same sentence as CTNNB1 in open-access papers (continued):
Sharing a sentence is not in itself a finding about the gene and the disease.
melanoma (continued). "Besides, it has been seen that overexpression of CTNNB1 in CTCs has prognostic value in both cancers, melanoma and pancreatic." (PMID 34071445, 2021). "We found that ABCB5 was differentially co-expressed in a cluster of 0D5P cells with the transcription factor MITF and CTNNB1, whose expression may be enriched in melanoma stem-cell populations." (PMID 32157095, 2020). "Together, these observations delineate that MYC and CTNNB1 may act as immune exclusion molecules in MITF‐positive melanoma tumors." (PMID 32147909, 2020). "Furthermore, the CTNNB1 promotes expression, in a positive feedback loop, of Tspan8, which triggers melanoma cell detachment and invasiveness." (PMID 32850962, 2020). "After the knockdown by lentiviral expression of CTNNB1 specific shRNA in the 451Lu melanoma cells a reduced cytoplasmic and nuclear protein level became evident when compared with invading 451Lu melanoma cells that showed a higher expression of cytoplasmic and nuclear β-catenin." (PMID 29454361, 2018). "For B16F10, CTNNB1 (β-catenin) was significantly upregulated while almost all chemokines were suppressed, indicating a possible link to melanoma intrinsic β-catenin signaling which suppresses chemokine production from tumor cells and prevents T cell infiltration." (PMID 30388137, 2018). "Because CTNNB1 mutations usually co-occur with mutations in the other 5 genes, we defined pan-negative samples as those melanomas negative for mutations in the 5 remaining genes." (PMID 25537510, 2015). "Thus, our results demonstrate that depletion of PKN1 can synergize with WNT3A stimulation to promote apoptosis in malignant melanoma cells, and this effect requires CTNNB1." (PMID 24114839, 2013). "Previous work has demonstrated that forced expression of a non-degradable phosphorylation mutant of CTNNB1 can increase the metastatic potential of melanoma cells harboring activating mutations in the NRAS/phosphatidylinositol 3-kinase pathways." (PMID 24114839, 2013). "Melanomas also harbor mutations that promote the malignant phenotype, such as in BRAF, CDKN2A, PTEN, CTNNB1, NRAS, PIK3CA and KIT, but except for BRAF (∼50%) and common loss of CDKN2A, these mutations exist in a minor portion of melanoma specimens (10% or less)." (PMID 19234609, 2009). "Identification of 55 patients with stage IV melanoma with APC/CTNNB1 genetic aberrations allowed us to understand their role in predicting response to immunotherapies more robustly than the eight, stage IV patients with APC/CTNNB1 somatic mutations from the TCGA SKCM cohort." (PMID 34986841, 2022). "In addition, CTNNB1 is not mutated in other melanocytic tumors, such as Spitz nevi, blue nevi, or melanoma." (PMID 34205480, 2021). "In another study, while a CTNNB1 missense mutation and a truncating APC mutation were reported only in one out of forty cell lines, it has been demonstrated that hypermethylation of APC promoter was present in about 15% of melanoma biopsies and cell lines suggesting transcriptional silencing." (PMID 32659938, 2020). "At least 6 genes have been shown to be recurrently mutated in melanoma, including the serine-threonine kinase encoded by BRAF; the receptor tyrosine kinase encoded by KIT; the GTP-binding proteins encoded by NRAS, GNA11, and GNAQ; and the WNT signaling pathway component encoded by CTNNB1." (PMID 22536370, 2012). "We present data from two independent melanoma patient cohorts in which the β-catenin pathway has been investigated by DNA sequencing of the APC and CTNNB1 gene." (PMID 34986841, 2022). "Our data showed that DAPT blockade in melanoma leads to the up-regulation of AXIN1, CSNK2A3, CEBPA2, CTNNB1, and c-myc genes in tumors." (PMID 32695658, 2020).
melanoma (continued). "The cordycepin treatment downregulated the expression of ZEB1, HMGA2 and TWIST1 by more than 50% but had minimal effects on ADAM9, RAC1, SALL4, CTNNB1, ZEB2 and YES1 in these two melanoma cell lines." (PMID 25868853, 2015). "Following treatment of A375 melanoma cells with WNT3A, phosphorylation sites on CTNNB1 typically regulated by GSK3 become dephosphorylated, and as CTNNB1 accumulates, those sites are again phosphorylated (time course in lanes 1–4)." (PMID 24114839, 2013). "While the effect of CTNNB1 on the MEK pathway is unknown, E6201 provides insights into the mechanism of metastatic melanoma progression into brain metastasis." (PMID 36983983, 2023). "The results indicate that, as in the human melanomas, Mitf correlated well with expression of Ctnnb1, HDAC11 and Psen2, but unlike the human tumors Myc was not correlated with Mitf." (PMID 35771179, 2022). "In advanced disease, no clear characteristics distinguishing CTNNB1-mutant from other melanomas were observed; however, studies of larger, optimally prospective, cohorts are warranted." (PMID 36077603, 2022). "Unexpectedly, patients with MM and APC/CTNNB1 genetic aberrations demonstrate a slightly higher frequency and early (i.e., within the first six months) development of melanoma brain metastases (MBMs) compared to patients without." (PMID 34986841, 2022). "Nevertheless, the presence of APC/CTNNB1 genetic aberrations in stage IV melanoma does not diminish the clinical benefit from immunotherapies." (PMID 34986841, 2022). "The first cohort (TCGA SKCM) included patients with stage II-IV melanoma, was not enriched for APC/CTNNB1 mutations (approximately 11.5%, prospective analysis), and historically preceded FDA approval of PD1 inhibitors." (PMID 34986841, 2022). "They found that beta catenin 1 (CTNNB1) overexpression could serve as a potential CTC biomarker, suggestive of immune surveillance evasion, which supports studies in human melanoma immune escape mechanisms." (PMID 33925387, 2021). "These pathways include lipid biosynthesis and regulation (e.g., Steroid hormone biosynthesis, Steroid Biosynthesis, Statin pathway, cytochrome P450 activity), as well as proto‐oncogenic genes and cancer (e.g., {CTNNB1, 130} [Static Module], {FLI1, 10} [Static Module], Melanoma [KEGG])." (PMID 29773677, 2018). "To test whether CTNNB1 is required for the increased apoptosis in melanoma cells that we observed upon depleting PKN1, we transfected A375 malignant melanoma cells with siRNAs targeting PKN1 and CTNNB1 individually and in combination." (PMID 24114839, 2013). "Re-sequencing of CTNNB1 exon 3 revealed D32H, and not S37F substitution reported before, in our 501 mel cells, and S33C mutation in YURIF melanoma tumor and cultured cells, whereas the gene in all the other cell strains was normal." (PMID 19234609, 2009). "Conversely, Ctnnb1 expression was prominent in melanoma, but virtually absent in MPNSTs." (PMID 41063628, 2025). "Transcriptomic expression of CTNNB1 was not elevated in CTNNB1-mutant melanoma." (PMID 36077603, 2022). "APC/CTNNB1 genetic aberrations are not enriched in non-inflamed melanomas." (PMID 34986841, 2022).
melanoma (continued). "Interestingly, mutations in the TERT promoter region were only present in tumors identified as melanoma, and not in benign CTNNB1-mutant melanocytic tumors." (PMID 36077603, 2022). "In addition to activation of the non-canonical signaling pathways, WNT5a was reported to activate the canonical CTNNB1 pathway in the presence of FZD4 receptors in melanoma cells." (PMID 32546756, 2020). "Unfortunately, similar experiments could not be conducted with YURIF melanoma cells because transfection with CTNNB1-directed siRNA failed to produce any reduction in β-catenin protein (data not shown)." (PMID 19234609, 2009). "Melanoma-intrinsic activated β-catenin pathway, the product of the catenin beta 1 (CTNNB1) gene, has been associated with low/absent tumor-infiltrating lymphocytes, accelerated tumor growth, metastases development, and resistance to anti-PD-L1/anti-CTLA-4 agents in mouse melanoma models." (PMID 34986841, 2022). "We identified 55 patients with stage IV melanoma and APC/CTNNB1 genetic aberrations (mut) and 169 patients without (wt)." (PMID 34986841, 2022).
gastric cancer (74 papers, 2012 to 2025). A primary or metastatic malignant neoplasm involving the stomach. "Among these, gastric cancer and pathways in cancer were the two key pathways associated with CTNNB1 and CDH1." (PMID 40150405, 2025). "CTNNB1’s mutations have been found to cause aberrant WNT/CTNNB1 signaling and are associated with the susceptibility and prognosis of breast, endometrial, and gastric cancers." (PMID 35846154, 2022). "CTNNB1 mutations occur in up to 26% of gastric cancers and are associated with nuclear localization of β-catenin." (PMID 35358569, 2022). "Several CTNNB1 single-nucleotide polymorphisms are associated with gastric cancer susceptibility and prognosis." (PMID 35358569, 2022). "5, 5, 3, and 2 mutations of KRAS, PIK3CA, ERBB2 and CTNNB1 were observed in 4, 4, 3, and 2 gastric cancers, respectively (5, 3, 3, and 2 hotspot mutations, respectively)." (PMID 34873204, 2021). "Among 145 mutations within 31 genes detected in gastroesophageal junction carcinomas and gastric adenocarcinoma, mutations in APC and CTNNB1 are more prevalent among gastric carcinomas, with more than three driver mutations detected in gastric carcinomas." (PMID 34488905, 2021). "We also observed similar changes in post-transfection expression of EphA2 and CTNNB1 (encoding β-catenin) with the EphA2-expressing vector in gastric cancer cells BGC823 and AGS, which indicated β-catenin is closely regulated by EphA2." (PMID 30451837, 2018). "Two components of the Wnt pathway, APC and CTNNB1, were in aggregate mutated more frequently in gastric carcinomas than in GEJ tumors (16% vs. 3%, p = 0.006)." (PMID 25656989, 2015). "Mutations in the Wnt pathway components APC and CTNNB1 were more common among gastric carcinomas (16% vs. 3%, p = 0.006), and gastric carcinomas were more likely to have ≥3 driver mutations detected (11% vs. 2%, p = 0.044)." (PMID 25656989, 2015). "Mutations of CTNNB1 were significantly more frequent in EBV-associated gastric carcinoma (P = 0.046)." (PMID 22723903, 2012). "Studies also revealed the existence of single nucleotide polymorphisms (SNPs) in the CTNNB1 gene as well as in the Axin1 gene, indicating that Wnt signaling may be related to the different congenital risks for developing gastric cancer." (PMID 31248166, 2019). "GJB4, which has close relationship with tumors, increased the proliferation and metastasis of gastric cancer cells through Wnt/catenin beta 1 (Wnt/CTNNB1)." (PMID 40575171, 2025). "A previous study demonstrated that nuclear MYH9 bound to the CTNNB1 promoter and promote CTNNB1 transcription, thereby conferring resistance to anoikis in gastric cancer." (PMID 40115777, 2025). "Dysregulated Wnt signaling affects almost 50% of gastric cancers, with the most commonly mutated genes being RNF43, AXIN1/2, CTNNB1, and APC." (PMID 39191487, 2024). "CTNNB1 genes are present in gastric cancer and are involved in the signaling mechanisms of gastric cancer along with various molecules." (PMID 38612999, 2024). "Nevertheless, CTNNB1 simultaneously activated the ‘Pathways in cancer’ and ‘Gastric cancer’ pathways." (PMID 39062881, 2024). "Previous research has demonstrated that, in a gastric cancer model in mice, Myosin IIA can bind to the promoter region of the Ctnnb1 gene in gastric cancer cells, mediating its transcriptional expression." (PMID 39404399, 2024). "The inhibited transcription activity of CTNNB1 has also been observed to be coincident with restrained progression of gastric cancer and the inactivation of the Wnt/β-catenin signaling pathway." (PMID 37076452, 2023). "LncRNA HCG11 has been experimentally demonstrated to facilitate the proliferation and migration of gastric cancer cells through the miR-1276/CTNNB1/Wnt pathway." (PMID 36693898, 2023). "Conversely, in five of these genes, all clonally mutated patients had mutations that were likely pathogenic (CTNNB1, ELF3, ATM, KMT2E, and PIK3CA), lending stronger support to their candidate gastric cancer driver status." (PMID 36970058, 2022).
gastric cancer (continued). "Recently, it was confirmed that MYH9 binds to the CTNNB1 promoter to promote CTNNB1 transcription, conferring resistance to anoikis in gastric cancer." (PMID 34887392, 2021). "SNHG10 facilitates gastric cancer cell proliferation and migration by targeting the miR-495/CTNNB1 axis and activating the WNT pathway." (PMID 34676212, 2021). "Previous studies have shown that CTNNB1 is mostly related to the occurrence and development of tumors, including Craniopharyngioma, Hepatocellular and Gastric cancer, Studies have also shown that CTNNB1 has an important relationship with heart development." (PMID 33891565, 2021). "In this study, we uncovered that MYH9-induced CTNNB1 transcription promoted the peritoneal metastasis of gastric cancer cells." (PMID 32685004, 2020). "Meanwhile, stable transfection of two shRNAs targeting the junction of circ-HuR resulted in its down-regulation and up-regulation of HuR and its downstream genes (CCND2 and CTNNB1) in gastric cancer cells." (PMID 31718709, 2019). "CACNA1G was associated with the most complex molecular network, which included several G-proteins and CTNNB1, a proto-oncogene that drives gastric cancer cells’ epithelial-to-mesenchymal transition." (PMID 28846697, 2017). "Previous data also showed that CTNNB1 (1–9 %) and KRAS (5–6 %) mutations were relatively uncommon in gastric cancer." (PMID 27782820, 2016). "The genes targeted by AMK in the context of gastric cancer include apoptosis regulator Bcl-2 (BCL2), catenin beta 1 (CTNNB1), B-cell stimulatory factor 2 (IL6), mutated in multiple advanced cancers 1 (PTEN), proto-oncogene (SRC), and tumor necrosis factor ligand member 2 (TNF)." (PMID 38612999, 2024). "In addition, some gastric cancer cell lines used in this study suffer mutations in APC (HGC27, MKN45, and MKN28) or CTNNB1 (AGS)." (PMID 35805009, 2022). "Upon the analysis of the TCGA dataset of 415 human gastric cancer tissue samples and 34 normal stomach samples, a dramatic increase in the mRNA levels of β-catenin (CTNNB1) and its downstream target genes, such as cMyc, CyclinD1 (CCND1), and MMP2, was observed in human gastric cancer tissue samples." (PMID 36551233, 2022). "Indeed, genetic mutations in components of this pathway such as APC, AXIN1/2 and CTNNB1 are well-established molecular events in colorectal, as well as gastric carcinomas and HCC." (PMID 22768190, 2012). "Functional validation using siRNA-mediated knockdown in MNK45 and AGS cell lines demonstrated that COL4A1 and CTNNB1 play essential roles in maintaining tumor cell proliferation, clonogenic survival, and migratory potential, confirming their functional importance in gastric cancer progression." (PMID 41291892, 2025). "Emerging evidence has demonstrated that Wnt/β‐catenin is activated after gastric cancer and plays a critical role in promoting invasion and migration through overexpressing or increasing the functions of several components of the Wnt pathway such as Wnt1, Wnt2, Wnt3, Wnt5a, Fzd‐3, CTNNB1 and LRP6." (PMID 28994231, 2018). "Our observed upregulation of CTNNB1 and COL4A1 is consistent with earlier studies reporting elevated expression of these genes in gastric cancer tissues, particularly in the presence of H. pylori infection." (PMID 41291892, 2025).